INS (insulin)
Diseases named in the same sentence as INS in open-access papers (continued):
Sharing a sentence is not in itself a finding about the gene and the disease.
Hyperglycemia (continued). "Aspalathin, a dihydrochalcone C-glucoside of rooibos, reduced hyperglycemia and ameliorated glucose intolerance through increased glucose uptake and insulin secretion in db/db mice." (PMID 23662132, 2013). "In T2D, pancreatic β cells are continuously activated to synthesize and secret insulin due to unresolved hyperglycemia, and this cellular stress gradually induces deterioration and apoptosis of pancreatic β cells." (PMID 23781214, 2013). "In vivo substitution of insulin to correct hyperglycaemia prevented the increased injury observed in flip−/− mice and was accompanied by a significant reduction in the number of TUNEL-positive hepatocytes and caspase-3 activation." (PMID 23828575, 2013). "Insulin gene expression is suppressed by oxidative stress in β-cells when hyperglycemia results in lowering insulin secretion." (PMID 23691063, 2013). "The alkaloid 1-ephedrine promotes the regeneration of islets of the pancreas, following destruction of the beta cells, hence restoring the secretion of insulin and thus corrects hyperglycemia." (PMID 23847458, 2013). "In summary, the results suggest that aerosolized insulin alleviates inflammatory responses augmented by hyperglycemia in acute lung injury." (PMID 23622115, 2013). "Parallel with hyperglycemia, serum insulin levels were significantly increased in ZDF rats compared to lean ones during the 25 weeks showing the presence of hyperinsulinemia in ZDF animals." (PMID 23320804, 2013). "Liver-specific deletion of GCK leads to hyperglycemia due to defects in glucose metabolism and impacts on insulin secretion in response to glucose." (PMID 23573289, 2013). "Curiously, despite marked hyperglycemia it produced, the glucose-loaded diet elicited a weak insulin secretory response, although insulin concentration still exceeded that recorded in cats eating the high protein diet without added glucose." (PMID 24348462, 2013). "And after 8 weeks, hyperglycemia degenerates and insulin secretion of the islets stimulated by glucose is more severely impaired, but generally, during its lifetime, fasting glucose remains mild and stable and rises only after challenge with glucose." (PMID 23671868, 2013). "Haploinsufficiency of Mll2 results in hyperglycaemia and hyperinsulinaemia at fasting and impaired glucose tolerance with blunted insulin secretion in response to a glucose load." (PMID 23826075, 2013). "Metformin reduces hyperglycemia by suppressing hepatic glucose output (hepatic gluconeogenesis), increasing insulin sensitivity and enhancing peripheral glucose uptake." (PMID 23724063, 2013). "An understanding of the molecular pathways involved in insulin secretion is useful in explaining such clinical observations as the ability of GLP-1R agonists to reduce hyperglycaemia with a low likelihood of hypoglycaemia." (PMID 22776039, 2013). "Low insulin sensitivity has a pathophysiological effect on metabolic syndromes, including central obesity, dyslipidemia, hyperglycemia, hypertension, impaired fibrinolysis, and atherosclerosis." (PMID 24282409, 2013). "Hyperglycaemia and insulin resistance have been identified as key players in the development of diabetic atherosclerosis, with metabolic insulin signalling being an important contributor to normal vascular function and homeostasis." (PMID 24369540, 2013). "We propose that an interaction between circulating glucose and the systemic inflammatory response syndrome propagates hyperglycemia by inducing pancreatic dysfunction in combination with profound insulin resistance in peripheral metabolic tissues." (PMID 23826335, 2013). "These subjects also have a rapid gastric emptying leading to hyperglycaemia followed by high insulin and hypoglycaemia." (PMID 23704713, 2013).
Hyperglycemia (continued). "To confirm that cytopiloyne reduced hyperglycemia by stimulating insulin production from pancreatic β cells in vivo, we tested its ability to reduce hyperglycemia and to augment insulin levels in STZ-treated C57BL mice whose β cells were already depleted." (PMID 23573144, 2013). "Hyperglycemia and fasting plasma insulin showed autosomal dominant inheritance, while impaired insulin secretion and epididymal fat accumulation showed an autosomal recessive mode of inheritance." (PMID 23671880, 2013). "These mice fed a high-fat diet for a short period of time (3–8 weeks) become obese and severely insulin resistant and develop postglucose load hyperglycemia, fasting hyperinsulinemia, and a diminished first phase insulin response." (PMID 23762879, 2013). "Most of the patients presented with a severe hyperglycaemia, which required an intensive care monitoring and an aggressive insulin therapy to normalize the blood glucose levels." (PMID 23762090, 2013). "Other considerable risk factors for developing ROP are low IGF-1 levels, poor nutritional intake, hyperglycaemia, insulin treatment, corticosteroid treatment, insufficient intake of DHA and, of course, fluctuating/high oxygen concentrations." (PMID 24069180, 2013). "Uncontrolled state of hyperglycemia due to defects in insulin secretion/action leads to a variety of complications including peripheral vascular diseases, nephropathy, neuropathy, retinopathy, morbidity, and/or mortality." (PMID 26317014, 2013). "Transplanting these differentiated cells into streptozotocin-induced immunodeficient diabetic mice led to the reversal of hyperglycemia, and more than 18% of the cells in the grafts expressed insulin at 6 weeks after transplantation." (PMID 24260156, 2013). "It presents mild-to-severe hyperglycemia, glucose intolerance, raised glycosylated hemoglobin concentration, depletion of pancreatic insulin stores, and dysfunction of insulin secretion." (PMID 23476801, 2013). "We cannot exclude that acute insulin discontinuation and hyperglycemia have different effects in males and females." (PMID 23308171, 2013). "The development of T2DM requires both IR and inadequate insulin secretion, leading to persistent hyperglycemia." (PMID 23367493, 2013). "Both acute and chronic exenatide therapy improved β-cell secretory function (i.e., insulin secretion in response to hyperglycemia)." (PMID 23256660, 2013). "Deletion of p47phox reduced kidney hypertrophy, oxidative stress and mesangial matrix expansion, and also reduced hyperglycaemia by increasing pancreatic and circulating insulin concentrations in the Akita mouse." (PMID 23457509, 2013). "Conversely, when insulin secretion is suppressed, acute hyperglycemia during intravenous glucose administration increases plasma IL-6 concentrations." (PMID 23776669, 2013). "IGF-1 is a peptide growth factor that shares approximately 50% sequence homology with insulin and is produced primarily by the liver following stimulation mainly by growth hormone, as well as hyperinsulinemia and hyperglycemia." (PMID 23819063, 2013). "TAM-mediated beta cell-specific inactivation of Glis3 in adult mice downregulates insulin expression, leading to hyperglycaemia and subsequently enhanced beta cell apoptosis." (PMID 23197416, 2013). "Nude mice were injected with STZ to eliminate endogenous β-cells, and received an implantable insulin pellet to control excessive hyperglycemia." (PMID 23671681, 2013). "These mice exhibit severe hyperglycemia 2-3 weeks after birth due to β-cell-specific damage in response to overexpression of calmodulin transgene regulated by the insulin promoter." (PMID 23844375, 2013). "In GK rats, reduction in β-cell mass occurs during their fetal development followed by mild hyperglycemia that appears post weaning at the age of 3–4 weeks after birth which impairs the ability of β-cells to secrete insulin in response of increase glucose." (PMID 23409091, 2013).
Hyperglycemia (continued). "Among these, appropriate insulin secretion from pancreatic β-cells seems to play a major role in compensating for GC-induced hyperglycemia." (PMID 24312573, 2013). "In conclusion, the long-term use of CSII therapy persistently mimics physiological insulin secretion to reduce hyperglycemia-induced oxidative stress and consequently is beneficial to the recovery of islet function." (PMID 24223662, 2013). "These rats also had reduced fasting plasma insulin concentrations (Figure 3aii), suggestive of β-cell dysfunction, and increased glycohemoglobin (GHb) (Figure 3aiii), indicative of chronic hyperglycemia." (PMID 24145577, 2013). "It has also been reported that increased insulin secretion from hypertrophic pancreatic islets delayed the onset of hyperglycemia in high-fat diet-fed SDT rats." (PMID 23691526, 2013). "It is of considerable interest that the acute effects of whey protein on postprandial blood glucose are comparable to sulfonylureas and other insulin secretagogues used for the pharmaceutical management of hyperglycaemia in T2DM." (PMID 23822206, 2013). "This disease is characterized mainly by hyperglycemia and insufficient insulin secretion or resistance to insulin by tissues." (PMID 23476801, 2013). "Due to its pharmacodynamic profile, insulin glargine substitutes basal insulin secretion effectively controlling morning glycaemia, whereas fast acting insulin reduces postprandial hyperglycaemia." (PMID 23916120, 2013). "This research is part of the Stroke Hyperglycemia Insulin Network Effort (SHINE) trial, Identification Number NCT01369069." (PMID 24499406, 2013). "The injection of rAAV-lep increases hypothalamic leptin expression and moderates diet-induced hyperglycemia, hyperinsulinemia, and skeletal muscle insulin resistance." (PMID 23579596, 2013). "The hyperglycemia was found able to inhibit the response of aortic rings to insulin and apparently the female vascular endothelium is more sensitive to the toxic effect of hyperglycemia than the male vascular endothelium." (PMID 23536959, 2013). "Three infants received insulin in the first week of life for hyperglycemia and 10 infants received postnatal steroids." (PMID 24220185, 2013). "Rodents injected with STZ not only develop hyperglycemia with decreased insulin level, but show increased serum FFA, cholesterol and triglyceride levels and metabolic dysfunction in hearts." (PMID 23922853, 2013). "Serotransferrin plays a role in the stimulation of cell proliferation; it can also act as an insulin antagonist, producing acute hyperglycemia in normoglycemic rats and ketonuria in diabetic rats." (PMID 24015209, 2013). "Although the safety profile of pasireotide was similar to that of conventional SSA's in terms of gastrointestinal symptoms and gallstones, higher frequency of hyperglycaemia was observed and is thought to be due to decreased insulin and incretin secretion." (PMID 24616766, 2013). "Instead, the game-theoretic theory we have presented relates a conductance decrease to an adaptive response of an islet that sacrifices strong gap junctions in order to maintain insulin control over hyperglycemia." (PMID 23936417, 2013). "For instance, HbA1c has been shown to correlate positively with DNA methylation of INS and PDX-1 in human pancreatic islets and hyperglycaemia was associated with increased DNA methylation of the same genes in clonal β cells cultured in vitro." (PMID 23879380, 2013). "Down-regulation of IRS-1 mRNA expression in skeletal muscle inhibited the stimulatory effect of insulin on glucose utilization further contributing to hyperglycemia." (PMID 24312573, 2013). "Two mechanisms are predominantly responsible for hyperglycemia secondary to GC: a decrease in insulin secretion and insulin sensitivity." (PMID 23557386, 2013).
Hyperglycemia (continued). "This study employed a well-established in vivo mouse model to explore the role of insulin in treating acute myocardial ischemia/reperfusion injury and in restoring the effects of ischemic preconditioning during acute hyperglycemia." (PMID 24371503, 2013). "These mutations permanently “lock in” the KATP channel in an open state, leading to insufficient insulin release and severe hyperglycemia within the first six months of life." (PMID 23762547, 2013). "As hyperglycaemia per se has been reported to downregulate insulin expression as well as stimulate beta cell apoptosis, we used two strategies to circumvent these effects of hyperglycaemia in the TAM-treated Glis3fl/fl/Pdx1CreERT+ mice." (PMID 23197416, 2013). "For the sepsis management bundle, only three centers reported using insulin in case of hyperglycemia (glycemia 10.5 mmol/L)." (PMID 23497713, 2013). "The currently enrolling Stroke Hyperglycemia Insulin Network Effort (SHINE) trial employs responder analysis for its primary efficacy outcome." (PMID 24499406, 2013). "Some serotonergic antidepressants reduce hyperglycaemia and increase the insulin sensitivity whereas some noradrenergic antidepressants have opposite effects." (PMID 24354794, 2013). "Recently, it was demonstrated that SNE ameliorated hyperglycemia, dyslipidemia and improved the whole body insulin sensitivity in T2DM rats." (PMID 23862157, 2013). "A fatty liver has been shown to be insulin resistant and also overproduces glucose, which can lead to hyperglycaemia." (PMID 24236183, 2013). "It is likely that other comorbidities that are present in hospitalized patients alter the action or secretion of insulin and anticipate the onset of hyperglycemia." (PMID 23557386, 2013). "Its neuron-sparing effect was initially attributed to the ability of insulin to reduce post-ischemic hyperglycemia, a condition known to be neurodegenerative." (PMID 24223835, 2013). "T2DM is a very heterogeneous condition; we should expect that patients with predominantly fasting hyperglycemia would have a better response to basal insulin only, while those with mainly post-prandial hyperglycemia are obvious candidates for prandial insulin." (PMID 24348585, 2013). "Rats in the DH group had persistent hyperglycemia and rats in the DN group that were treated with insulin had blood glucose levels near control values." (PMID 23762878, 2013). "The combination of parenteral glucose support and the systemic inflammatory response in the acute phase of sepsis induces profound insulin resistance and impairs compensatory pancreatic insulin secretion, leading to the development of fulminant hyperglycemia." (PMID 23826335, 2013). "IPCs express the pancreatic β-cells developmental genes such as pancreatic and duodenal homeobox-1 (PDX-1) or functional genes such as insulin, and glucagon and secrete insulin in response to glucose that reverses hyperglycemia in drug-induced diabetic mice." (PMID 23648189, 2013). "Acute hyperglycaemia is a common acute adrenergic signal of stress and is present in myocardial infarction, whereas increased catecholamine levels result in decreased insulin secretion and increased insulin resistance." (PMID 23399749, 2013). "Downstream of an insulin resistant liver, increased plasma FFA levels disrupt the glucose-fatty acid or Randle cycle and insulin-mediated glucose uptake by skeletal muscle, facilitating the development of hyperglycemia." (PMID 23356701, 2013). "Stem cell therapy is a promising alternative for islet transplantation in type 2 diabetic patients who fail to control hyperglycemia even with insulin injection." (PMID 23762531, 2013). "Drug-induced hyperglycemia is a clinical condition that can occur as a result of impaired insulin secretion or action or the destruction of pancreatic beta cells." (PMID 23557386, 2013).
Hyperglycemia (continued). "GK rats are lean and develop mild hyperglycemia early in life due to impaired insulin secretion, in particular a consistently low insulin response to glucose stimulation." (PMID 24319481, 2013). "A prospective study on the role of glucose metabolism in breast cancer incidence justified that hyperglycemia among insulin resistant women exhibits direct correlation with mammary cancer risk." (PMID 23061769, 2013). "Type 1 diabetes (T1D) is characterized by hyperglycemia due to lost or damaged islet insulin-producing β-cells." (PMID 23762878, 2013). "Male ZDF rats become hyperlipidemic, hyperinsulinemic and insulin resistant by 7–8 weeks of age and subsequently hyperglycemia sets in the presence of marked hyperinsulinemia." (PMID 23692921, 2013). "Recombinant methionyl human leptin (r-metHuLeptin) has been reported to be useful in controlling hyperglycemia, insulin levels, and HbA1c in patients with RMS and other lipodystrophy syndromes." (PMID 23367497, 2013). "In vivo study demonstrated reversal of hyperglycemia and an increase in serum insulin levels in the rats transplanted with SDF-1α pre-conditioned IPCs." (PMID 23648189, 2013). "The term DM describes a metabolic disorder of multiple etiologies characterized by chronic hyperglycemia with disturbances of carbohydrate, fat and protein metabolism resulting from defects in insulin secretion or insulin action or both." (PMID 24354866, 2013). "They both presented with severe daytime hyperglycemia due to the binding of IA to insulin and early morning hypoglycemia due to the separation of antibodies from insulin." (PMID 23424687, 2013). "When grafted in vivo, the mixed progeny transplanted under the kidney capsule of STZ-induced diabetic mice can reverse hyperglycemia, and this by producing physiological amounts of insulin for a given glucose load." (PMID 23671681, 2013). "Improved glucose and lipid metabolism, together with a reduction in hyperglycemia and hypercholesterolemia, as well as improved insulin sensitivity, have been observed in people following a high fiber intake." (PMID 24244650, 2013). "ZnT3, ZnT5 and ZnT8 gene expression are differentially regulated by glucose in INS-IE cells, and streptozotocin-treated ZnT3 null mice have decreased insulin gene expression and insulin secretion that resulted in hyperglycemia." (PMID 24265765, 2013). "The basis for therapeutic use as an anti-diabetic drugs is because the activation of PPAR-γ leads to improve insulin sensitivity and lower serum glucose during hyperglycemia." (PMID 24041200, 2013). "An insulin deficient model, where STZ has been widely used to produce insulin deficiency via pancreatic β-cell destruction, a significant hyperglycemia with hypoinsulinemia were developed within 2 weeks." (PMID 23717483, 2013). "Intraperitoneal glucose tolerance test (IPGT) demonstrated in vivo glucose-responsive changes in insulin levels to correct hyperglycemia within 45 minutes." (PMID 23826312, 2013). "The combination of reduced glucose metabolism and insulin-resistance leads to constant hyperglycaemia in the fasting as well as in the postprandial state." (PMID 23983688, 2013). "Based on clinical, including anemia and deafness, and paraclinical findings, TRMA was diagnosed and insulin therapy was started to correct the hyperglycemia." (PMID 23454484, 2013). "Intraperitoneal STZ injection to the animals results in a prompt pancreatic β-cells destruction, diminish the insulin levels and induce significant hyperglycemia." (PMID 23384060, 2013). "Following 15-day treatment, hot aqueous extract of F. deltoidea stimulated insulin release and reduced fasting hyperglycemia." (PMID 22701507, 2012). "The liver, one of the insulin-sensitive tissues, plays a pivotal role in the processes of hyperglycemia and dyslipidemia." (PMID 23320036, 2012).